MDK (midkine)
Diseases named in the same sentence as MDK in open-access papers (continued):
Sharing a sentence is not in itself a finding about the gene and the disease.
melanoma (24 papers, 2016 to 2026). A malignant, usually aggressive tumor composed of atypical, neoplastic melanocytes. "Similar to our findings, PTN family member MDK was associated with immune checkpoint blockade unresponsive melanoma." (PMID 36828390, 2023). "These MetAlert mice, together with loss‐ and gain‐of‐function studies in melanoma cell lines and histopathological studies in human clinical biopsies, ultimately identified the growth factor Midkine (MDK) as a key driver of neolymphangiogenesis and metastasis." (PMID 34762341, 2021). "Recently, it has been shown that in primary melanomas, distant lymph nodes and organs may increase their lymphatic vessel density as a pre-metastatic niche to favor and promote distant metastases through the tumor secretion of midkine (encoded by MDK)." (PMID 29349517, 2018). "In conclusion, the interplay between cancer cells and CAFs mediated by the BGN/MDK axis is a critical driver of malignancy in melanoma, highlighting it as a promising therapeutic target for intervention." (PMID 41833003, 2026). "In malignant melanoma, MDK secreted by tumor cells promotes immune suppression and facilitates immune evasion, thereby enhancing tumor development." (PMID 40500394, 2025). "Melanoma cells overexpress the protein biomarkers midkine (MDK) and CD276 (B7-H3), which appear to have increased expression during malignancy." (PMID 41463631, 2025). "MDK can promote macrophage infiltration into melanoma tumors, and it promotes expression of TGF-β and interleukin 13—markers of immunosuppressed environments." (PMID 40429950, 2025). "Studies in melanoma models have demonstrated that genetically targeting MDK can overcome resistance to PD-1/PD-L1 inhibitors and enhance therapeutic efficacy." (PMID 41246334, 2025). "MDK is overexpressed in a variety of cancer types, including melanoma, glioblastoma, neuroblastoma, esophageal, breast, lung, prostate, colon, and others." (PMID 41463631, 2025). "The results above raise the possibility that POSTN or MDK expression in melanoma mediate emergence of TTR macrophages and, as a consequence, resistance formation." (PMID 38942020, 2024). "Since our FNA technology failed to capture CAFs, we investigated POSTN and MDK expression in the tumor microenvironment of targeted therapy-resistant melanoma biopsies using the Tumor Profiler dataset." (PMID 38942020, 2024). "MDK secretion by melanoma cells leads to an immune evasive microenvironment that favors immune suppression and cancer development in malignant melanoma." (PMID 37240085, 2023). "Recent published data suggest that MDK-driven modulation is important for immune evasion in melanomas with activation of NFKB signaling cascade, which in turn can promote dysfunction in CD8+ T cells and negatively affect their anti-tumor cytotoxicity." (PMID 36973261, 2023). "In melanoma, midkine overexpression gives rise to an immunosuppressive tumor microenvironment via promoting intratumoral recruitment of myeloid cells and tumor-associated macrophages." (PMID 36906597, 2023). "A discrepancy between RNA and protein expression levels was also true for a recent study of a PTN family member, MDK, in melanoma, thus, highlighting the need to evaluate protein levels for these small growth factors." (PMID 36828390, 2023). "Midkine plays an important role in maintaining immunosuppressive microenvironment of melanoma and gallbladder cancer." (PMID 36906597, 2023). "In melanomas, MDK effectively trains macrophages and cytotoxic T cells to prevent the immune system from attacking and recognizing the cancer cells." (PMID 37240085, 2023). "For example, MDK was reported to reconstruct immunosuppressive environment in melanoma and gallbladder cancer." (PMID 37081869, 2023). "MDK was primarily secreted by melanoma cells and interacted with multiple cell types in LN+AM, whereas it was secreted by fibroblasts and endothelial cells in LN-AM." (PMID 38065972, 2023).
melanoma (continued). "We interrogated MDK as this is a new inducer of neolymphangiogenesis and melanoma metastasis we recently described with prognostic features in human clinical biopsies." (PMID 34762341, 2021). "These two blocking antibodies prevented the reduction of MDK expression by BO‐110 in melanoma cells, even increasing its levels." (PMID 34762341, 2021). "BO‐110 was found to reduce about 70–60% MDK mRNA levels in melanoma cell lines of different genetic backgrounds that recapitulate main protumorigenic mutations characteristic of this disease." (PMID 34762341, 2021). "To this end, we generated subcutaneous xenografts of high‐MDK‐expressing melanoma cells: the murine B16R2L and the human SK‐Mel‐147 for analyses of drug response in immune‐competent and T‐cell‐deficient MetAlert mice, respectively." (PMID 34762341, 2021). "The secretion of MDK by melanoma cells affects the expression of VEGFR3 on lymphatic endothelial cells through the paracrine effect of the mTOR pathway." (PMID 34759262, 2021). "This repressive activity of BO‐110 on MDK mRNA expression results in a marked, and also early, blockade of MDK secretion by melanoma cells." (PMID 34762341, 2021). "Of note, recent results have shown that MDK plays a paracrine role in the regulation of lymphatic endothelial cells during melanoma metastasis." (PMID 32308772, 2020). "In melanoma cells MDK activates mTOR to promote lymphangiogenesis." (PMID 40429950, 2025). "Moreover, single-cell RNA sequencing in glioblastoma and melanoma has highlighted MDK as a niche-specific stromal factor contributing to immune evasion and resistance to checkpoint blockade therapies." (PMID 40500394, 2025). "As MDK is a systemic lymphangiogenesis-inducing factor, its detection might function as a prognostic marker for melanoma patients." (PMID 38098484, 2023). "In melanoma, MDK activates mTOR via a similar signaling pathway, leading to an increased expression of vascular endothelial growth factor receptor 3 (VEGFR3) and the stimulation of lymphangiogenic signals, resulting in metastatic growth in lymph nodes and the lungs." (PMID 38098484, 2023). "In addition, midkine plays a vital role in maintaining immunosuppressive tumor microenvironment of melanoma and gallbladder cancer." (PMID 36906597, 2023). "Interestingly, a recent study found a positive correlation between MDK expression and poor prognosis in melanoma patients and revealed that MDK-educated melanoma secretome promotes immunosuppressive macrophages leading to T-cell dysfunction." (PMID 36028490, 2022). "Thus, neither POSTN nor MDK altered the susceptibility of melanoma cells to MEKi-induced cell death." (PMID 38942020, 2024). "Moreover, midkine (MDK), a protein related to PTN, was recently reported to be associated with aggressive immune evasive melanoma, suggesting that these small heparin-binding neurotrophic factors might have unexplored important functions in malignancy." (PMID 36828390, 2023). "Moreover, using blocking antibodies against midkine, a cytokine that induces lymphangiogenesis in distant organs, may suppress lymph node metastasis formation in melanoma." (PMID 32260071, 2020). "As POSTN and MDK were unable to directly drive resistance in melanoma cells, we examined the cell populations that could be affected by POSTN or MDK." (PMID 38942020, 2024). "It is expressed in keratinocytes, not melanoma cells, but recombinant midkine stimulates cell proliferation." (PMID 27689402, 2016). "To test whether POSTN or MDK could directly affect the responsiveness of melanoma cells to MAPK inhibitors, we first identified primary melanoma cell lines displaying either high or low endogenous POSTN and MDK expression (M150325, M131205 and M150543, M161201, respectively)." (PMID 38942020, 2024).
melanoma (continued). "Next, we interrogated the expression profile of hLECs to determine to which extent the response to BO‐110 involved signaling cascades shared (or not) with melanoma cells, as a strategy to identify possible common modulators of MDK and VEGFR3 in the two cell types." (PMID 34762341, 2021). "The role of midkine in melanoma pathogenesis has not yet been investigated." (PMID 27689402, 2016).
hepatocellular carcinoma (22 papers, 2003 to 2026). A malignant tumor that arises from hepatocytes. "In hepatocellular carcinoma, MDK was associated with enhanced Treg and myeloid-derived suppressor cell (MDSC) infiltration and enhanced expression of immune checkpoint molecules such as cytotoxic T-lymphocyte-associated protein 4 (CTLA4)." (PMID 40429950, 2025). "In conclusion, serum MDK may serve as a novel diagnostic tumor marker for the detection of hepatocellular carcinomas, particularly in patients with AFP <20 ng/mL and/or at an early stage." (PMID 25737783, 2015). "Transcriptomic and proteomic analyses from large-scale datasets such as TCGA and CPTAC have demonstrated that MDK is consistently overexpressed in aggressive tumor types, including hepatocellular carcinoma, lung adenocarcinoma, and ovarian cancer." (PMID 40500394, 2025). "In hepatocellular carcinoma, MDK overexpression decreased the expression of programmed death ligand 1 (PD-L1) in MDSCs, promoting immunosuppression and reducing the cytotoxicity of T cells." (PMID 40429950, 2025). "Upregulated MDK expression in tumor tissues is associated with tumor growth in many cancers, including non‐SCLC (NSCLC), hepatocellular carcinoma, and bladder cancer." (PMID 40620228, 2025). "Although its expression in normal adult tissues is barely detectable, MDK serum levels are found to be elevated in several types of cancer, including hepatocellular carcinoma (HCC)." (PMID 38247828, 2024). "In this study, we found serum MDK was significantly elevated in patients with hepatocellular carcinomas compared with liver cirrhosis patients (median: 0.625 versus 0.15 ng/mL) and the healthy controls (median: 0.625 versus 0.125 ng/mL)." (PMID 25737783, 2015). "A number of strategies to inhibit midkine expression/signaling are under investigation, and successful suppression of hepatocellular carcinoma growth by midkine-antisense oligonucleotide-loaded nanoparticles has already been reported." (PMID 22562257, 2012). "As the HIF-1α binding site in MDK’s promoter would suggest, hypoxia promotes MDK expression in the lungs of mice as well as human PMNs, monocytes, HUVECs, glioblastoma, hepatocellular carcinoma, and non-small-cell lung cancer." (PMID 40429950, 2025). "In hepatocellular carcinoma (HCC), MDK mediates anoikis resistance to the circulatory tumor cells (CTCs) and enhances tumor metastasis and relapse upon binding to ALK receptors through the PI3K/Akt/NFκB/TrkB axis, which makes a positive feedback loop." (PMID 37240085, 2023). "Antisense oligonucleotide targeting MDK has also shown significant inhibition of hepatocellular carcinoma (HCC) and enhanced the chemosensitivity of the HCC towards Adriamycin." (PMID 37240085, 2023). "Midkine is overexpressed in hepatocellular carcinoma (HCC) and plays a role in tumor progression, but less is known about its role in resistance of circulating tumor cells (CTCs) to anoikis which leading to recurrence and metastasis." (PMID 28430645, 2017). "Mounting evidence has indicated that MDK plays a significant role in carcinogenesis-related activities, such as proliferation, migration, antiapoptosis, mitogenesis, transformation, and angiogenesis, in many types of solid tumors, including hepatocellular carcinomas." (PMID 25737783, 2015). "However, the diagnostic value of serum MDK for hepatocellular carcinomas, particularly for those at the early stage, has not yet been investigated in Egypt." (PMID 25737783, 2015). "Notably, MDK is overexpressed in hepatocellular carcinoma (HCC), where it contributes to both drug resistance and apoptosis inhibition." (PMID 40500394, 2025). "In hepatocellular carcinoma (HCC), MDK enables a discrete discrimination of patients with early HCC from those with cirrhosis." (PMID 38098484, 2023). "In hepatocellular carcinoma, lncRNA ZFAS1 potentiates the development of hepatocellular carcinoma via the miR-624/MDK/ERK/JNK/P38 signaling pathway." (PMID 36855431, 2023).
hepatocellular carcinoma (continued). "These indicate that MDK is a novel marker and superior to AFP with a lower false-positive rate in diagnosing and differentiating hepatocellular carcinomas from liver cirrhosis." (PMID 25737783, 2015). "Subgroup 0 included hepatoma cells specifically expressing GPC3, CD24 and MDK." (PMID 37305578, 2023). "For the completion of this narrative review, a literature search was performed via the PubMed, Scopus and Science Direct databases using the following keywords: HCC, hepatocellular carcinoma, MDK, midkine, NEGF-2, MK, and AFP." (PMID 38247828, 2024). "Thus, combination of MDK and APF may be a promising strategy for early diagnosis of hepatocellular carcinomas in the future." (PMID 25737783, 2015). "We examined the expression of the midkine (MK) and α-fetoprotein (AFP) genes in 15 paired human specimens obtained from hepatocellular carcinoma (HCC) and the corresponding noncancerous regions of the same patients." (PMID 12966430, 2003).
gastric cancer (21 papers, 2011 to 2025). A primary or metastatic malignant neoplasm involving the stomach. "MDK secreted from cancer-associated fibroblasts promoted the expression of EMT genes in gastric cancer via the PI3K/AKT pathway, and through this conferred cisplatin resistance." (PMID 40429950, 2025). "Midkine has previously been reported to be upregulated in cervical, bladder, esophageal and gastric cancers and increased levels of midkine are associated with poor prognosis." (PMID 36016386, 2022). "Midkine is a heparin-binding growth factor, which was highly expressed in various malignant tumors and the increased expression of midkine was significantly associated with the advanced clinical stage and distant metastasis of gastric cancer." (PMID 21672207, 2011). "High MDK protein expression has been reported in several cancer types and associated with the cancer progression, including gastric cancer, pancreatic cancer, lung cancer, breast cancer, colorectal carcinoma, esophageal cancer, hepatocellular carcinoma and bladder cancer." (PMID 29872508, 2018). "To evaluate the potential role of the MDK-NCL signaling axis in lymph node metastasis of gastric cancer, we first analyzed its expression patterns using pan-cancer data from the TCGA library." (PMID 41249133, 2025). "Conversely, siRNA-mediated silencing of MDK in SNU-638 human gastric cancer cells led to increased sensitivity to these agents, including 5-FU, doxorubicin, and cisplatin." (PMID 40500394, 2025). "In gastric cancer, MDK overexpression upregulates P‐AKT and P‐ERK expression, thereby inducing resistance to adriamycin." (PMID 40620228, 2025). "Ovarian estrogen secretion promotes ovarian metastasis of gastric cancers by enhancing the secretion of MDK by fibroblasts." (PMID 40429950, 2025). "For instance, CXCL-14 secreted by CAFs upregulates LINC00092 in ovarian cancer, and Midkine upregulates ST7-AS1 in gastric cancer." (PMID 39717771, 2024). "Serum midkine levels of gastric cancer patients were significantly higher (p = 0.02) than those of the healthy controls." (PMID 37240085, 2023). "A group studied around 250 genes showing altered expression in 5-fluorouracil, cisplatin, or doxorubicin-resistant gastric cancer cell lines and found that MDK is overexpressed in all these cell types suggesting MDK as a multidrug-resistant gene." (PMID 37240085, 2023). "In gastric cancer cells, it is found that MDK induces the P38 signaling, thereby activating AP1 and increasing transcription of MHC class I chain-related proteins A and B (MICA/B)." (PMID 37240085, 2023). "MDK was found to support progression of gastric cancer, and increased EGFR signaling under hypoxia through interaction with NCL." (PMID 37081869, 2023). "In human tissue samples of prostatic and hepatocellular carcinomas, increased protein levels of MDK have been detected via immunohistochemical staining, while mRNA levels of MDK were increased in human gastric carcinoma specimens." (PMID 38098484, 2023). "Midkine (MK) and cyclooxygenase-2 (Cox-2M and Cox-2L) demonstrate high transcriptional activity in cell-lines from gastric cancer and represent promising elements for incorporation into CRAds." (PMID 29534501, 2018). "A single-cell study of ovarian metastases from gastric cancer reported that estrogen-responsive (ER-positive) ovarian fibroblasts secrete midkine (MDK) under estrogen stimulation, which engages LRP1 on gastric cancer cells and promotes migration, invasion, and metastatic colonization." (PMID 41323395, 2025). "Furthermore, MDK was overexpressed in drug-resistant gastric cancer cell sublines compared with the parental drug-sensitive ones." (PMID 35625997, 2022). "Our previous study found that STC-1 gene could be activated in human gastric cancer BGC823 cells with over-expressed midkine." (PMID 21672207, 2011).
gastric cancer (continued). "Finally, through integrated single-cell and spatial analysis, we observed that gastric cancer cells may remodel the tumor microenvironment via the MDK-NCL signaling pathway." (PMID 41249133, 2025). "Additionally, cancer-associated fibroblasts (CAFs) mediate chemoresistance against cisplatin in gastric cancer cells via MDK, which up-regulates long non-coding RNA (LncRNA) suppressor of tumorigenicity seven antisense RNA1 (ST7-AS1) which activates PI3K/Akt pathway and promotes EMT." (PMID 37240085, 2023). "Similarly, in a gastric cancer cell line, when MDK was silenced, there was a decrease in cell survival, indicating that a reduction of MDK might be involved in chemosensitization." (PMID 37240085, 2023). "In this study, we explored the major ligands and receptors of the MK signaling pathway, such as MDK-NCL, which were involved in the progression of various cancers, including lung cancer, breast cancer, liver cancer, gastric cancer, and colorectal cancer." (PMID 40496867, 2025). "Midkine, another cytokine, upregulates ANRIL in oral squamous cell carcinoma, leading to cisplatin resistance, and it similarly promotes ST7-AS1 in gastric cancer, enhancing cisplatin resistance." (PMID 39717771, 2024). "Another study found that MDK activated AKT and ERK pathways and induced the Adriamycin resistance in gastric cancer cell." (PMID 30001734, 2018). "Previous studies showed that MDK activated both the Akt and ERK1/2 pathways, upregulated the expression of several cell-cycle-related proteins and promoted gastric cancer cell survival and growth." (PMID 30001734, 2018). "This implied that the MDK-NCL signaling plays a key role in MLN and may contribute to the spread of gastric cancer." (PMID 41249133, 2025). "CAFs secrete Midkine, which elevates the expression of ST7-AS1 in gastric cancer cells." (PMID 39717771, 2024). "When it came to tumor type, high expression of MDK was significantly related to shorter OS in patients with pancreatic cancer, gastric cancer, NSCLC and other cancers, while MDK had no relevance with OS in the patients with OSCC or HNSCC." (PMID 29872508, 2018).